PFN2 (profilin 2)
Diseases named in the same sentence as PFN2 in open-access papers (continued):
Sharing a sentence is not in itself a finding about the gene and the disease.
neuroblastoma (1 paper, 2014). Neuroblastoma (NB) is the most common solid, extracranial childhood tumor. "Analysis of N1E-115 neuroblastoma cell line for differentiation related cytoskeletal proteins also indicated profilin 2 to be elevated in expression." (PMID 25084196, 2014).
Obesity (1 paper, 2011). Accumulation of substantial excess body fat. "However, two of the genes, Prkacb and Pfn2, have not previously been implicated in any feeding/obesity paradigms." (PMID 22087873, 2011).
prostate adenocarcinoma (1 paper, 2022). "Thus, we analyzed SNTB1 and PFN2 gene expression in prostate adenocarcinoma tissues using Oncomine." (PMID 35413990, 2022).
Salmonella Infections (1 paper, 2023). Infections with bacteria of the genus SALMONELLA. "Contrary to our expectation, Salmonella infection was also enriched in clusters 1 and 3, and thus, we reviewed the DEGs and found that only six DEGs, such as AHNAK, MAP2K1, MAPK10, ARL8B, IL6, and PFN2, were enriched after S. enterica BNCC186354 infection, but only ARL8B and PFN2 were downregulated." (PMID 36980306, 2023).
staphylococcus aureus infection (1 paper, 2020). An infectious process in which the bacteria Staphylococcus aureus is present. "In human patients with pulmonary nontuberculous mycobacteria, four-point mutations of PFN2 have been identified, and macrophages expressing these mutant versions of PFN2 are unable to control Salmonella typhimurium or Staphylococcus aureus infection." (PMID 32064340, 2020).
tumor (27 papers, 2016 to 2025). "Because cancer cell migration and invasion are prerequisites for metastasis, PFN2 OE significantly promoted proliferation, migration, and invasion, demonstrating a novel mechanism underlying PFN2 mediated tumor metastasis." (PMID 33234737, 2020). "Importantly, through integrative machine learning approaches, we identified four hub genes (MGP, LOXL2, FSTL3, and PFN2) that are closely associated with tumor development and progression." (PMID 41395115, 2025). "Moreover, PFN2 expression is positively associated with tumor invasion depth and lymph node metastasis." (PMID 34917619, 2021). "Our findings revealed that the mRNA levels of Pfn2, Taldo1, and Ftcd were significantly downregulated in tumor tissues of Hepa1‐6 implantation models." (PMID 40018995, 2025). "Profilin 2 (PFN2) has emerged as an essential factor in tumor development and progression within its isoforms." (PMID 40299352, 2025). "Through the robust machine learning approaches, we developed a four‐gene model (MGP, LOXL2, FSTL3, and PFN2) reflecting key biological processes associated with inflammatory CAF activity and tumor aggressiveness." (PMID 41395115, 2025). "IHC representative images from HPA database indicated that FSTL3 and PFN2 were highly expressed in tumor samples." (PMID 41395115, 2025). "PFN2, an actin cytoskeleton regulator, plays a crucial role in cell motility, with its function varying across different tumor types." (PMID 41551597, 2025). "Knockdown of PFN2 significantly inhibits tumor cell growth, proposing PFN2 targeting as a potential therapeutic avenue for CRPC." (PMID 39055653, 2024). "The finding in this report that the tumor-suppressive clustered miRNAs, miR-1/133 cluster, directly regulated PFN2 in HNSCC cells is attractive and novel." (PMID 35327465, 2022). "Recently, we revealed that PFN2 was directly regulated by tumor-suppressive miR-1/miR-133 clustered miRNAs in HNSCC cells, and its overexpression promoted cancer cell malignant transformation." (PMID 35886008, 2022). "Similar to the in vitro results, qRT-PCR and immunohistochemistry of harvested tumor specimens showed that both PFN2 and SNTB1 expression levels in the tumors were reduced by each siRNA." (PMID 35413990, 2022). "However, another study suggested a different result: the degree of tumor metastasis is negatively associated with PFN2 expression level likely because of the enhancement in EMT induced by low PFN2 levels considering that enhanced EMT may increase migratory capabilities." (PMID 34917619, 2021). "In HNSCC, PFN2 enhances tumour invasiveness via epithelial-mesenchymal transition (EMT)." (PMID 40475773, 2025). "Interestingly, in OSCC, PFN2 exhibits an opposing role by inhibiting tumor growth and aggressiveness, highlighting the context-dependent functions of PFN2 in cancer." (PMID 40299352, 2025). "PFN2 promotes tumour angiogenesis within the tumour microenvironment via cancer-derived exosomes." (PMID 40475773, 2025). "Among PFN Isoforms, profilin 2 (PFN2) has been known to play key roles in tumor progression." (PMID 35479278, 2022). "Our studies indicated that PFN2 promoted SCLC development by enhancing tumor angiogenesis." (PMID 33234737, 2020). "Furthermore, we revealed that PFN2 regulated tumor angiogenesis in the tumor microenvironment through cancer-derived exosomes." (PMID 33234737, 2020). "Since BC recurrence involves either metastatic or locoregional outgrowth of therapy-resistant tumour cells, we interrogated the effects of Pfn1 and Pfn2 transcript levels on the RFS and the OS of BC patients (3951 samples) using pre-assembled transcriptome datasets available from kmplot.com." (PMID 30318519, 2018). "In sum, PFN2 assumes a tumor-promoting role in ESCC progression and metastasis by inducing EMT." (PMID 27188458, 2016). "In oral squamous cell carcinoma (OSCC), PFN2 inhibits tumor growth and aggressiveness." (PMID 27188458, 2016).
tumor (continued). "Notably, knockdown of PFN2 showed a marked inhibitory effect on tumor growth in vivo." (PMID 35413990, 2022). "In endothelial cells, exosomal LYPLAL1-DT enhances angiogenesis by modulating miR-204-5p, PFN2, and SIRT1 levels, underscoring its critical role in tumor progression and vascular remodeling." (PMID 41551597, 2025). "On this basis, we verified that exosomes derived from HUVECs and tumor cells containing LYPLAL1-DT were efficiently internalized by SCLC cells, leading to decreased miR-204-5p levels and increased PFN2 and BCL2 expression in the recipient tumor cells." (PMID 41551597, 2025). "Recently, the growth, metastasis, and angiogenesis of small cell lung cancer (SCLC) by profilin 2 (PFN2) was reported, which triggered vascular formation and angiogenesis via tumor-derived exosomes." (PMID 35892884, 2022). "There are different regulatory axes in the same tumor, such as enhancing ESCC cell proliferation through miR-188-5p/PFN2 or interacting with miR-338-3P/miR-362-3p to activate E2F1 expression." (PMID 34372871, 2021). "PFN2 OE or enriched presence of PFN2 in exosomes significantly promoted SCLC tumor cell growth in vitro and in vivo; PFN2 also enhanced tumor angiogenesis through exosomes." (PMID 33234737, 2020). "Taken together, our study revealed the role of PFN2 in SCLC development and metastasis, as well as tumor angiogenesis through exosomes, providing a new molecular target for SCLC treatment." (PMID 33234737, 2020). "Similarly, in endothelial cells, tumor cell-derived exosomal LYPLAL1-DT downregulated miR-204-5p, resulting in elevated levels of both PFN2 and SIRT1." (PMID 41551597, 2025). "In addition, Cox proportional hazards regression analysis was performed for 5-year overall survival rates, using each gene expression level (i.e., PFN2, PSEN1, and SYT1), tumor stage, pathological grade, and age as covariates." (PMID 35327465, 2022). "Furthermore, SBF2-AS1 directly inhibits miR-494, resulting in the increased expression of profilin 2 (PFN2) and accelerated tumor progression." (PMID 34372871, 2021). "Specifically, we found that genes involved in regulation of cell lineage transition and tumor progression including inhibitor of differentiation 1 (ID1), actin cytoskeletal regulator PFN2 and ID334–39 are among the top of the upregulated genes in ENZ-R cells compared to control cells." (PMID 33750801, 2021).
cancer (21 papers, 2008 to 2025). A tumor composed of atypical neoplastic, often pleomorphic cells that invade other tissues. "While its role in various cancers remains underexplored, PFN2 overexpression has been confirmed in HNSCC clinical specimens, where it enhances cancer cell migration and invasion." (PMID 40299352, 2025). "Several studies have reported that PFN2 expression is involved in malignant transformation of cancer cells." (PMID 35327465, 2022). "PFN2 overexpression reduced epithelial markers and increased mesenchymal markers in several cancers." (PMID 35327465, 2022). "Whereas there was almost no PFN2 expression in the normal epithelium, high expression of PFN2 was detected in cancer lesions in HNSCC." (PMID 35327465, 2022). "Our present analysis showed that aberrantly expressed PFN2 facilitated cancer cell migration and invasion and was closely involved in the malignant phenotypes of HNSCC." (PMID 35327465, 2022). "Overexpression of PFN2 was confirmed in clinical specimens, and its aberrant expression facilitated cancer cell migration and invasion abilities." (PMID 35327465, 2022). "Next, we reorganized the mRNAs that significantly correlated with cancer progression and linked their upstream miRNA and lncRNA, such as ISPD-AS1-has-miR-148a-5p-SMAD5, and PARD6G-AS1-has-miR-493-5p-PFN2." (PMID 33859940, 2021). "Furthermore, results of the previous studies highlighted that the expression of PFN2 was significantly high, and it was co‐expressed with lncRNAs in various cancers." (PMID 41354645, 2025). "Each gene in the risk evaluator, PLXNA1, MARCKSL1, IQGAP3, PFN2, PON1, and TAK, has been reported to be associated with the prognosis or progression of cancer." (PMID 37954858, 2023). "Similarly, molecules including long noncoding RNA SLCO4A1-AS1, Hsa_circ_0003159, and circle RNA circABCB10 which modulates PFN2 were found to interact with miR-223-3p to regulate cancer progression." (PMID 35509814, 2022). "Overexpression of PFN2 was reported in several types of cancers, including HNSCC." (PMID 35886008, 2022). "In conclusion, PFN2 plays an important role in a variety of cancers and could be an important biomarker for different cancer cells, as well as an attractive therapeutic target." (PMID 34917619, 2021). "Recently, PFN2 has emerged as a key regulator of cancer development and progression." (PMID 34917619, 2021). "Recently, PFN2 have emerged as significant regulators of cancer processes." (PMID 27188458, 2016). "Moreover, aberrant expression of PFN2 facilitated cancer cell migration and invasion." (PMID 35327465, 2022). "On the other hand, a new set of potential biomarkers (NCKAP1, TNFRSF12A, LAMB2, FKBP9, PFN2, TOM1L1) and expression rules for the identification of different cancers at the transcriptome level were discovered." (PMID 34917619, 2021). "PFN2 is an epigenetic regulator of SMAD2/3 (Mothers against decapentaplegic homolog 2/3), which in turn has been shown to promote metastasis in cancer cells." (PMID 32183695, 2020). "Moreover, in vitro assays revealed the biological role of PFN2 in facilitating the migration and invasion of cancer cells by regulating the EMT phenotype of ESCC, thereby proving that PFN2 might be a potential biomarker for the diagnosis and a therapeutic target for the treatment of ESCC." (PMID 27188458, 2016). "PFN2 may also function as an independent prognostic biomarker and chemotherapeutic target for ESCC patients from Han and Kazakh ethnic populations, particularly those who are suffering from early stages of cancer." (PMID 27188458, 2016).
infection (2 papers, 2020 to 2023). The state of being infected such as from the introduction of a foreign agent such as serum, vaccine, antigenic substance or organism. "Knockdown or deletion of PFN2 renders isolated cells and whole animals susceptible to infection, morbidity, and, in many cases, death." (PMID 32064340, 2020). "Because of the presence of a canonical MAC-perforin (MACPF) domain, PFN2 has been proposed to form functional pores in bacterial membranes, leading to bacterial death and control of infection." (PMID 32064340, 2020).
neurodevelopmental disorder (1 paper, 2025). A behavioral and cognitive disorder with onset during the developmental period that involves impaired or aberrant development of intellectual, motor, or social functions. "The profilin 2 (Pfn2) conventional knock-out (ko) mouse model (Pfn2−/−) is viable and has been already shown to display synaptic, physiological, and behavioral phenotypes typical of neurodevelopmental disorders." (PMID 40078324, 2025).
neurological disorders (1 paper, 2025). "However, current knowledge on PFN2 function in brain, as well as the data presented in this work, would support its standing as a risk gene for neurological disorders, including ASD." (PMID 40078324, 2025).
PFN2 also shares sentences with these, for which no sentence is quoted: amyotrophic lateral sclerosis (1 paper); Ataxia (1); bacterial infection (1); colon cancer (1); colorectal tumors (1); depression (1); diabetic nephropathy (1); dystrophin deficiency (1); glioblastoma (1); hypospadias (1); non-small cell lung carcinoma (1); oral cancer (1); Parkinson disease (1); primary immunodeficiency (1); rectal cancer (1); viral infections (1).